IL6 (interleukin 6)
Diseases named in the same sentence as IL6 in open-access papers (continued):
Sharing a sentence is not in itself a finding about the gene and the disease.
steatosis (continued). "Furthermore, Quer reduced liver lipid steatosis and inhibited the expression of proinflammatory cytokines, such as tumor necrosis factor-α, IL-6, and IL-1β." (PMID 33076582, 2020). "IL-6-deficient mice display a milder NAFLD severity and antibody mediated IL-6 receptor (IL-6R) neutralization improved liver damage in mice fed methionine choline deficient (MCD) diet, despite enhanced steatosis." (PMID 31921154, 2019). "Treating mice with BAR501 improved liver histopathology leading to a 50–70% reduction in the steatosis, fibrosis and inflammatory scores, along with reduction of inflammatory (Il-1β, Il-6, Tnfα, Mcp-1, Rantes and F4/80) and fibrogenic (αSma and Col1α1) genes (P < 0.05)." (PMID 29057935, 2017). "Likewise, the inhibition of the lipogenic enzyme expression shown here after IL-6 administration should, to a certain extent, compensate the HFD-induced steatosis but it also suggests a failure in IL-6-mediated signalling." (PMID 27333268, 2016). "Thus, in accordance with these observations and other reported findings, we anticipated that the administration of exogenous IL-6 would ameliorate the steatosis observed in IL-6−/− mice fed a HFD by increasing AMPK activity and CPT1 expression." (PMID 26035386, 2015). "The administration of exogenous IL-6 has been previously reported to protect against steatosis." (PMID 26035386, 2015). "However, its anti-inflammatory, hepatoprotective effects are contingent on the expression of other cytokines, and its inhibitory effect on IL-6 expression can delay liver regeneration and increase steatosis." (PMID 26695748, 2015). "Moreover, the steatosis in IL-6−/− mice exposed to a HFD was further exacerbated by rIL-6 treatment." (PMID 26035386, 2015). "In the fourth study, NASH could be well distinguished from simple steatosis when using the cutoff value of IL-6 at 4.6 pg/mL (AUROC 0.817, sensitivity 58.1%, specificity 100%)." (PMID 24252302, 2013). "These pathways activate the pro-inflammatory cytokines interleukin 6 (IL-6) and tumor necrosis factor alpha (TNF-α), which function as cytoprotective agents by reducing the expression of molecules associated with cancer and inhibiting the development of liver tumors related to steatosis." (PMID 39595613, 2024). "Interestingly, several proteins associated with steatosis and fibrosis were significantly correlated with markers of cholesterol metabolism (VLDL, HDL, triglycerides), inflammation (CD14, CD163, IL6), as well as cardiometabolic diseases, HIV-specific parameters, and ART, but not with SNPs." (PMID 39426127, 2024). "In grafts in the absence of steatosis obtained from DBDs, we observed that the administration of exogenous NO (BD+NO+LT) increased IL-6 and that this was associated with reduced IL-1β levels and protection against hepatic damage and inflammation, compared to the BD+LT group." (PMID 37593740, 2023). "The underlying mechanism of the effect of IL-6 on steatosis is not yet fully clear." (PMID 34221262, 2021). "Therefore, in the DEX group with higher TNF-α and IL-6 expression levels, this suggests that steatosis may be related to Kupffer cell dysfunction or activation, TGF-β signaling increased in fatty livers with inflammation." (PMID 30424542, 2018). "However, the chronic IL-6 replacement in IL-6−/− HFD-fed mice further aggravated steatosis." (PMID 26035386, 2015). "IL-10 may play a dual role in controlling liver injury via proinflammatory cytokine TNF-α inhibition and ethanol-induced steatosis, leading to potentiating alcoholic liver injury and ameliorating alcoholic liver injury, or via the inhibition of the hepatoprotective cytokine IL-6." (PMID 26508814, 2015). "However, as proposed by Gao (2012), using IL-6 in ex vivo treatment of donor livers to reverse minor organ damage (e.g., steatosis) before transplantation into ALD patients could have some utility." (PMID 26695748, 2015). "The lack of IL-6 expression was associated with exacerbated steatosis in HFD conditions." (PMID 26035386, 2015).
steatosis (continued). "Cytokines, particularly TNF-α, IL-1b and interleukin-6 (IL-6), are involved in the recruitment of circulating macrophages into the liver and the activation of Kupffer and hepatic stellate cells (HSCs), both contributing to the progression from simple steatosis to steatohepatitis." (PMID 25937854, 2014). "Common readouts include histological grading of steatosis, serum liver enzymes (ALT, AST), inflammatory cytokines (e.g., TNF-α, IL-6), insulin resistance indices, and gut microbiota profiling via 16S rRNA sequencing or metagenomics." (PMID 41001122, 2025). "The serum levels of IL-6 and VEGF were higher in patients with a histological diagnosis of MASH than in patients presenting only steatosis or a normal liver." (PMID 41172431, 2025). "miR-22 can regulate the inflammatory effects of steatosis by increasing the expression of the pro-inflammatory tumor necrosis factor α (TNF-α) and interleukin-6 (IL-6)." (PMID 39859495, 2025). "Specifically, the deletion of IL-10 results in IL-6/STAT3 mediated inflammatory response in the liver, decreasing steatosis." (PMID 41514930, 2025). "IL6 supplementation, as emerged from the fetal dataset, and simultaneous activation of the metabolic regulator FXR, prevents steatosis and promotes PHH proliferation, resulting in improved expansion of the derived organoids." (PMID 38740814, 2024). "EV-treated mice showed reduced levels of steatosis, liver damage (AST, ALT), liver triglycerides, total cholesterol, hepatic expression of TNF-α, IL-1, and IL-6, and restored insulin sensitivity." (PMID 39767754, 2024). "In steatosis and MASH, intrahepatic B cells secrete elevated levels of IL-6 and TNFα, which promote the activation of CD4 cells and their differentiation into Th1 cells." (PMID 39372417, 2024). "As a critical hallmark of NAFLD, immune cells typically increase at the transition from steatosis to NASH, leading to fibrosis through the release of cytokines like IL-6, IL-1β, IL-17, IL-22, TGF-β, and tumor necrosis factor-α (TNF-α)." (PMID 39273539, 2024). "In steatosis and MASH, intrahepatic B cells secrete elevated levels of IL-6 and TNF-α, which promote the activation of CD4 T cells and their differentiation into Th1 cells." (PMID 39372417, 2024). "Another study showed that IL-6 only demonstrated an elevation in NASH patients, but TNF-α significantly increased in all NAFLD categories, i.e., simple and moderate steatosis and NASH." (PMID 38535313, 2024). "During weeks 1 to 4, we noticed an upregulation of low‐grade chronic inflammatory cytokines (IL‐6 and IL‐13) and inflammatory chemokines (MIP‐1α and eotaxin), which concurred with the onset of steatosis." (PMID 38952069, 2024). "SIRT1 deficiency triggers the activation of the NF-κB pathway, leading to increased expression of inflammatory factors like IL-1β, IL-6, and TNF-α, accelerating the progression of NAFLD from simple steatosis to steatohepatitis." (PMID 39949396, 2024). "Compared with the control group, inulin reduced the steatosis lipid synthesis genes (CHREBP, Srebp-1c, FASN, and Scd-1) in mice fed a HFD and also significantly decreased the expressions of IL-6, IL-1β, and TNF-1α in the liver." (PMID 37554983, 2023). "In L02 cells, PA treatment notably intensified steatosis levels, elevated TRIM59 expression, and enhanced the secretion of tumor necrosis factor alpha (TNF-α), interleukin 6 (IL-6), and interleukin 8 (IL-8)." (PMID 37867509, 2023). "In conclusion, it seemed, after review, that most of the mentioned cellular and soluble mediators, with the exception of TNFα, IL-1β, IL-6 and hs-CRP, were more related to inflammation and fibrosis than steatosis itself." (PMID 36768637, 2023). "Amplifying the expression of TRIM59 further exacerbated steatosis and substantially heightened the secretion of TNF-α, IL-6 and IL-8." (PMID 37867509, 2023).
steatosis (continued). "Inflammatory biomarkers IL-1β, IL-6, IL-8, IL-10, and TNFα were all significantly elevated in the NAFLD/NASH patients, with respect to control participants and patients with simple steatosis." (PMID 36589452, 2022). "In a study of male rats, an 8-week exposure to 20% Fru (w/v) in drinking water led to significant increases in the expression of IL-6 and TNF-α in the liver, which was accompanied by obvious steatosis and pathological features of inflammation." (PMID 35495917, 2022). "Markedly higher levels of pro-inflammatory cytokines and chemokine, including TNF-α, IL-6, IL-18, and MCP-1 were detected in NASH serum than in those from the Non-steatosis group." (PMID 36209205, 2022). "Given that classically activated M1 macrophages showed increased levels of pro-inflammatory cytokines, including interleukin 1-β (IL-1β), tumor necrosis factor α (TNF α), interleukin 6 (IL6), which induce hepatic damage and steatosis." (PMID 35143415, 2022). "Of the top-ranked 10 genes, two genes (CYP7A1 and PEG10) were significantly up-regulated in both steatosis and NASH patients, while eight genes (FOSB, FOS, IL6, GADD45G, MYC, SLITRK3, JUNB, and IGFBP2) were significantly down-regulated." (PMID 33324350, 2020). "Up-regulation of several of these immune mediators (IL-6, IL-8, and MCP-1) was previously reported in liver cells and/or plasma of patients with steatosis and NASH, and correlated positively with the severity of liver inflammation and fibrosis." (PMID 33013934, 2020). "IL-6 is particularly relevant to NASH as it enhances the Ac-CoA pool, the hepatic glucose production and aggravates steatosis." (PMID 31959914, 2020). "Macrophage produced cytokines (e.g., IL-6, TNF, IL-1β) can directly target hepatocytes and promote steatosis, inflammation and hepatocellular damage." (PMID 31921154, 2019). "Previous report evaluated that genetically manipulated mouse model that showed activated IL-6 signaling and inactivated TGF-β signaling spontaneously developed liver tumors and steatosis." (PMID 31238892, 2019). "Furthermore, hepatic IL-6 has been shown to regulate glucose metabolism by increasing insulin sensitivity and negatively regulating hepatic glucose release to the periphery, maintaining liver tissue homeostasis and protecting against the progression of steatosis." (PMID 30818779, 2019). "IL-6 administration in DIO mice markedly raised circulating levels of lipids, glucose and leptin, elevated fat liver content and aggravated steatosis." (PMID 27333268, 2016). "To further understand the molecular mechanism by which IL-6 aggravates steatosis in HFD feeding, we examined the effects of the IL-6 replacement on the expression of hepatic lipogenic enzymes in IL-6−/− mice fed a HFD." (PMID 26035386, 2015). "Since Kupffer cells are the major producers of the cytokines that modulate TNF-α and IL-6 activity, higher TNF-α expression in our prenatal steroid group suggests that steatosis was related to Kupffer cell dysfunction or activation." (PMID 24822223, 2014). "HFD significantly increased total fat and triacylglyceride contents with macrovesicular steatosis, concomitantly with higher fasting serum glucose and insulin levels, HOMA, and serum TNF-α, IL-1β, and IL-6." (PMID 23082120, 2012). "The results also revealed that both IL-6 and IL-10 concentration was reduced in the liver, accompanied by lower apoB protein expression and resulting TAG accumulation (steatosis)." (PMID 20920329, 2010). "Infliximab (anti-TNF-α) reverses the steatosis and the expression of the proinflammatory markers (TNF-α, IL6, IL-1B) and improves insulin signal trasduction in a model of steatosis in rats." (PMID 18782455, 2008). "Although SFN-I induced a decreasing trend in steatosis score and levels of TG, TC, and IL-6, the difference was not statistically significant." (PMID 40427484, 2025).
steatosis (continued). "Considering that macrophages‐derived proinflammatory cytokines (IL‐1β, IL‐6, and TNF‐α) may regulate hepatocyte steatosis and apoptosis, we constructed a coculture system to observe whether a crosstalk exists between these two cell types." (PMID 39279458, 2024). "Although Shh drove the pathogenesis of NASH including steatosis, inflammation, and fibrosis, it did not induce the expressions of Il-1β, Tnf-α, and Il6 in bone marrow-derived macrophages (BMDMs)." (PMID 38342927, 2024). "Herein, we show new endogenous signaling pathways in LT from DBDs, namely, IL-6/IL-1β in non-steatotic liver grafts and IL-10/L-1β in steatotic ones; these different mechanisms that depend on the presence of steatosis had not been reported to date." (PMID 37593740, 2023). "Notably, NAFLD progression from simple steatosis to NASH, with substantial fibrosis, is mediated by inflammatory cytokines, including IL-1β, IL-6, and TNFα, overproduced by resident liver macrophages, i.e., the inflammatory-polarized M1-Kupffer cells." (PMID 37510108, 2023). "Steatosis is reported to lead to increased signaling of the transcription factor NF-κB, which can induce the production of pro-inflammatory mediators, such as TNF-α, IL-6 and IL-1β27." (PMID 37468618, 2023). "In addition, our results showed that XKY treatment significantly diminished hepatic lipid deposition and steatosis accompanied by improved liver function (ATL and AST), lipid profile (TC and TG) and inflammation (TNF-α and IL-6) in db/db mice." (PMID 37202792, 2023). "Steatosis induces the production of pro-inflammatory mediators like TNF-α, IL-6 and IL-1β." (PMID 37705071, 2023). "IL-6 not only induced STAT3 activation, leading to inflammation and liver damage, but also decreased the expression of sterol regulatory element binding protein-1 (SREBP1), alleviating steatosis." (PMID 36768637, 2023). "This proinflammatory cytokine was found to promote steatosis (by stimulating TG synthesis and cholesterol accumulation in the liver), inflammation (by upregulating ICAM-1 and inducing IL-6 and TNFα expression) and fibrosis (by activating HSCs and inducing the production of profibrogenic factors)." (PMID 36768637, 2023). "First, there was a ten-fold increase in IL6 levels following NM exposure in the NASH MT as compared to steatosis MT (i.e., 13 day exposure of TiO2 NMs at 10 μg/ml—steatosis MT 35.49 ± 1.44 pg/ml vs. NASH 438.8 ± 33.1 pg/ml), and this was sustained across all timepoints." (PMID 34668024, 2022). "The results showed that rosavin treatment significantly improved the liver function tests and lipid panel, decreased the hepatic expression of IL-6 and TNF-α proteins, and diminished the percentage and stage of steatosis, inflammation, and fibrosis as compared with the untreated NASH group." (PMID 36077546, 2022). "Mechanistically, constitutive methylated RIG-I at K18 and K146 enhances hepatic cholesterol synthesis and lipid accumulation, thus promoting steatosis and the following NASH and NASH-HCC, whereas JMJD4-demethylated RIG-I suppresses IL-6 response and inflammation-induced hepatocarcinogenesis." (PMID 36333807, 2022). "Together, we conclude that although hepatic RIG-I expression is increased in the first step steatosis stage to promote lipid accumulation and steatosis development, its expression is decreased in the following NASH and NASH-induced HCC, which is mediated by the proinflammatory cytokine IL-6." (PMID 36333807, 2022). "Despite significant correlation with steatosis, several factors such as IL-6, were not used in our index (MSI-S)." (PMID 35663311, 2022). "Indeed, the administration of germinated millet flour prevented hepatic inflammation and steatosis in HFD-fed animals by decreasing the hepatic levels of TNF-α and stimulating those of IL-6." (PMID 35565759, 2022).
steatosis (continued). "Steatosis in the WD30 group was confirmed by increased levels of tissue TGs and cholesterol, and inflammation by elevated levels of liver tumor necrosis factor alpha (TNF-α) and interleukin 6 (IL-6) (p < 0.01)." (PMID 34199098, 2021). "Therefore, miR‐22 can regulate inflammatory effects of steatosis by affecting the expression of the pro‐inflammatory factors TNF‐α and IL‐6." (PMID 33159388, 2021). "Inhibition of SYK could ameliorate the inflammation and steatosis of NAFLD by reducing the activation of macrophages and the production of CCl2, IL-6 and TNF-α." (PMID 34506234, 2021). "Steatosis in the WD group was confirmed by the increased level of the tissue triglycerides (TGs) and cholesterol, and mild inflammation by the level of liver tumor necrosis factor alpha (TNF-α) and interleukin 6 (IL-6)." (PMID 32046101, 2020). "In our study, it is also interesting to see increases in steatosis and ER stress without increases in serum IL-6 (systemic inflammation) or ALT (liver damage)." (PMID 33238880, 2020). "For instance, treatment with IL-6 ameliorated fatty liver by inducing STAT3 phosphorylation in ob/ob and HFD- induced obese mice, while deletion of IL-6 or hepatic STAT3 resulted in steatosis and hepatocellular damage in IL-10 knockout mice." (PMID 30038584, 2018). "In that case, the IL-6 administration restored the hepatic Stat3 phosphorylation under a HFD, as well as up-regulating the expression of the lipogenic enzymes and worsening the steatosis." (PMID 27333268, 2016). "In our assay conditions, even though chronic treatment with IL-6 aggravated the steatosis under a HFD, we observed no important inflammatory manifestations (e.g., lymphocyte infiltration) in liver samples." (PMID 27333268, 2016). "Chronic administration of exogenous IL-6 to HFD-fed IL-6–/– mice induced the overexpression of lipogenic enzymes, which probably contributed to enhanced liver lipogenesis and again increased steatosis." (PMID 26035386, 2015). "The HFD-fed IL-6−/− mice showed severe steatosis, no changes in CPT1 levels or AMPK activity, no increase in STAT3 amounts, inactivated STAT3, and marked downregulation of the expression of acetyl-CoA carboxylase (ACCα/β), FAS and SCD1." (PMID 26035386, 2015). "The aim of this study was to assess whether two-years treatment with Pirfenidone influences necroinflammation, fibrosis and steatosis, serum levels of TGF-β1, IL-6, TNF-α and CB1 and CB2 gene expression, in patients with chronic hepatitis C (CHC)." (PMID 25064094, 2014). "Multivariate logistic regression analysis identified the level of IL-6 > 4.81 pg/mL [odds ratio (OR): 33.7, 95% confidence interval (CI): 1.7-680.7, p ≤ 0.022] as an independent predictor of the degree of steatosis but not of NASH." (PMID 24252302, 2013). "In this model, IL-6 does not constitute the critical driving force for NASH but appears to modulate the inflammatory response rather than the initiation of the steatosis itself." (PMID 19936233, 2009). "It should be noted, however, that besides their important role as promoters of liver regeneration, TNF‐α and IL‐6 are both showing dichotomous negative effects in the liver, such as promoting cell death, liver toxicity, inflammation, and liver aging, fibrosis, steatosis, respectively." (PMID 40462652, 2025). "Tyrosol, in addition to improving steatosis, has been shown to ameliorate the inflammatory response triggered by a high-fat diet in mice by preventing up-regulation of JAK1 and STAT3 proteins and therefore of pro-inflammatory cytokines IL-6, tumor necrosis factor-α (TNF-α), and IL-10." (PMID 39452069, 2024). "Thus, depending on the presence or absence of steatosis, induction of BD downregulated different anti-inflammatory interleukins: IL-6 for non-steatotic and IL-10 for steatotic grafts." (PMID 37593740, 2023).